PIK3CA (phosphatidylinositol-4,5-bisphosphate 3-kinase catalytic subunit alpha)
Diseases named in the same sentence as PIK3CA in open-access papers (continued):
Sharing a sentence is not in itself a finding about the gene and the disease.
cyst (6 papers, 2017 to 2023). A sac-like closed membranous structure that may be empty or contain fluid or amorphous material. "The Matrigel invasion assay also revealed that PIK3CA mutant HOVs-cyst-1 cells and HOVs-cyst-1 cells, with both KRAS and PIK3CA mutations, showed higher invasion abilities than the other cells." (PMID 35326657, 2022). "This study successfully developed an in vitro carcinogenic model of LGSOCs by introducing oncogenic KRAS and PIK3CA gene mutations in immortalized HOVs-cyst-1 cells from serous cystadenomas." (PMID 35326657, 2022). "The established mouse xenograft tumors resulting from the inoculation of HOVs-cyst-1 cells with KRAS and PIK3CA mutations exhibited the micropapillary invasive pattern of LGSOCs with low nuclear atypia without alveoli." (PMID 35326657, 2022). "Statistical analysis showed that the proliferative, migratory, and invasive abilities of HOVs-cyst-1 cells, with both KRAS and PIK3CA mutations, were significantly higher than the corresponding abilities of the HOVs-cyst-1 cells (p < 0.01)." (PMID 35326657, 2022). "Furthermore, oncogenic mutations, KRAS and PIK3CA, were individually and simultaneously introduced in immortalized HOV-cyst-1 cells." (PMID 35326657, 2022). "Furthermore, analysis of the migration ability of the cells via an in vitro wound-healing assay showed that immortalized HOVs-cyst-1 cells, with both KRAS and PIK3CA mutations, had significantly (p < 0.01) higher migration abilities than HOVs-cyst-1 cells, with either KRAS or PIK3CA mutation." (PMID 35326657, 2022). "Conversely, the other cells (wild-type HOVs-cyst-1 cells or HOVs-cyst-1 cells, with either KRAS or PIK3CA mutation) did not induce tumor development in nude mice." (PMID 35326657, 2022). "HOVs-cyst-1 cells did not develop any colonies, whereas the double KRAS and PIK3CA mutant HOVs-cyst-1 cells, as well as HOVs-cyst-1 cells, with either KRAS or PIK3CA mutant, showed a small number of colonies compared with the SKOV3 cells." (PMID 35326657, 2022).
Hypoglycemia (6 papers, 2017 to 2025). A decreased concentration of glucose in the blood. "Defects in the PI3K/AKT/mTOR signaling pathway are considered among the genetic causes of recurrent hypoglycemia in childhood and hypoglycaemia is commonly observed in patients affected by overgrowth syndromes associated with mutations in the PIK3CA gene." (PMID 40354343, 2025). "As previously reported, we observed that the ubiquitous expression of an activating mutation in the Pik3ca gene (Pik3caH1047R) leads to severe hypoglycaemia and hypoinsulinemia, tissue growth and early death, in mice." (PMID 40354343, 2025). "We also did not observe any changes in food intake and efficiency ratio between control and Pik3ca mutant mice, therefore excluding changes in food intake as a contributing factor to the hypoglycaemia." (PMID 40354343, 2025). "A liver biopsy from P1 presented the opportunity to examine liver in one patient with PIK3CA-related hypoglycaemia." (PMID 28566443, 2017).
laryngeal carcinoma (6 papers, 2016 to 2026). Carcinoma that arises from the laryngeal epithelium. "PIK3CA (H1047R) mutation was more frequent in laryngeal carcinomas (20%, 8 cases in larynx vs 6%, 2 cases in hypopharynx) and was significantly associated with stage I-II tumors (P = 0.002), and negative lymph node metastasis (P = 0.003)." (PMID 27119232, 2016). "Multivariable Cox analysis further revealed PIK3CA gene amplification as an independent predictor of laryngeal cancer development." (PMID 38473941, 2024). "More importantly, this study uncovers PIK3CA gene amplification as a significant independent predictor of laryngeal cancer development beyond the current histopathological criteria." (PMID 38473941, 2024). "The combination of PIK3CA and SOX2 amplification also significantly predicted the laryngeal cancer risk (Log-rank test p = 0.033)." (PMID 38473941, 2024). "The PIK3CA and SOX2 amplifications were predominant in high-grade dysplasias and significantly associated with laryngeal cancer risk beyond histological criteria." (PMID 38473941, 2024). "PIK3CA gene amplification exhibits a more prominent role; it was detected in over 70% of progressing dysplasias, and unprecedentedly uncovered as a significant independent predictor of laryngeal cancer development." (PMID 38473941, 2024). "Furthermore, combined amplification of both the PIK3CA and SOX2 genes was found the strongest predictor of laryngeal cancer by ROC curve analysis (AUC = 0.675, p = 0.021)." (PMID 38473941, 2024). "Most of the observed PIK3CA mutations (8/9, 88.9%) occurred in patients without confirmed HPV infection (8/87, 9.2% in the HPV negative group) and with normal p16 expression (N = 85) in patients with laryngeal cancer." (PMID 34072735, 2021).
lobular breast cancer (6 papers, 2013 to 2024). "The dominant influence of mutations in CDH1 and PIK3CA reflects the recent results from TCGA showing that these two genes harbor by far the most frequently recurring mutations in lobular breast cancer." (PMID 27334989, 2016). "In patient 3, concordant activating mutations in the PIK3CA oncogene (H1047L) in both, the PT and the OM, further supported that the OM was derived from lobular breast cancer." (PMID 25355547, 2015). "In our study, we did not observe such enrichment for PIK3CA exon 9 mutations in lobular breast cancer." (PMID 24467828, 2014).
multiple myeloma (6 papers, 2016 to 2025). "We report here a hybrid-capture-based Liquid Biopsy Sequencing (LB-Seq) method used to sequence all protein-coding exons of KRAS, NRAS, BRAF, EGFR and PIK3CA in 64 cfDNA specimens from 53 myeloma patients to >20,000 × median coverage." (PMID 28492226, 2017). "Furthermore, only the blockade of PIK3CA is sufficient to induce cell death in a sizeable subgroup of MM samples, and PIK3CA inhibitor BYL-719 in combination treatments with other compounds establishes anti-myeloma agents resulted in strongly enhanced MM cell death." (PMID 32333246, 2020).
ovarian endometriosis (6 papers, 2020 to 2023). A non-neoplastic disorder characterized by the growth of endometrial tissue in the ovaries. "Our previous study clarified that PIK3CA, ARID1A, KRAS, FBWX7, and PPP2R1A are also frequently mutated in ovarian endometriosis." (PMID 38067342, 2023). "By multiregional sequencing, we demonstrated that epithelial cells with cancer-associated mutations such as oncogenic PIK3CA and KRAS mutations clonally expand in ovarian endometriosis without cancer." (PMID 33809880, 2021).
uterine carcinosarcoma (6 papers, 2018 to 2024). A usually aggressive malignant neoplasm arising from the uterine corpus and less often the cervix.
uterine tumor (6 papers, 2016 to 2024). "PIK3CA double mutations are quite common in breast and uterus tumors." (PMID 36808143, 2023).
viral infection (6 papers, 2019 to 2023). "The identification of virus infection pathways was an unexpected finding, but further analysis revealed that these virus-pathway associated genes had 12 genes in common, and 11 of these genes were also common to the PIK3CA pathway." (PMID 37005590, 2023). "Consistent with a previous report, the trinucleotide signatures were dominated by an association with age (signature 1) and the HPV positive lines demonstrated the APOBEC signature associated with underlying viral infection and an increased frequency of PIK3CA mutations." (PMID 34663790, 2021). "On the other hand, SDC4, PIK3CA, and IQGAP1 genes showed upregulated expression upon viral infection, and after mimic transfection and infection, their expression levels were decreased in hNP cells." (PMID 31578247, 2019). "Similarly, SDC4, PIK3CA, and CAV1 genes showed upregulated expression upon viral infection, and after miR-124-3p mimic transfection and infection, their expression levels were decreased in hNS1 cells." (PMID 31578247, 2019).
ameloblastoma (5 papers, 2018 to 2023). The most common odontogenic tumor, arising from the epithelial component of the embryonic tooth and usually affecting the molar-ramus region of the mandible or maxilla. "Additional mutations identified in mandibular ameloblastomas included JAK P132T, SMO, SMARCB1, PIK3CA, and CTNNB1." (PMID 38021761, 2023). "In maxillary ameloblastomas, additional mutations included BRAF L597R, FGFR2, PIK3CA, and SMO." (PMID 38021761, 2023). "Aside from the SMO mutations, APC mutations have been detected in 3/6 ameloblastomas, and CTNNB1, PIK3CA, SMARCB1, PTEN, CDKN2A mutations have been reported in a few cases and tend to occur in a non-mutually exclusive manner with BRAF p.V600E mutation and with each other." (PMID 35048058, 2021). "It is notable that the presence of two or three gene mutations, including somatic mutations in KRAS, PIK3CA, PTEN, FGFR, CDKN2A, and CTNNB1 in the background of either BRAF or SMO mutation-positive ameloblastomas, exclusively occurred in solid/conventional tumors." (PMID 35048058, 2021). "However, somatic KRAS, PIK3CA, PTEN, FGFR, CDKN2A, and CTNNB1 co-occurred also in the background of either BRAF- or SMO-mutated ameloblastomas." (PMID 29388014, 2018). "However, other Authors showed additional mutations to B-Raf in ameloblastomas, such as NRAS, HRAS, KRAS, FGFR2, and PIK3CA,10,23,44 suggesting they may represent secondary mutations occurring later in the pathogenesis of ameloblastoma." (PMID 35468886, 2022).
atherosclerosis (5 papers, 2023 to 2025). A disease characterized by the build-up of fatty material and calcium deposition in the arterial wall resulting in partial or complete occlusion of the arterial lumen. "The results of this study imply that targeting PIK3CA could potentially play a crucial role in the management of atherosclerosis by Tualang honey bioactive compounds." (PMID 37174317, 2023). "Finally, in vivo (rat/zebrafish) and in vitro (cell models) validations remain essential, exemplified by the Moluodan concentrated pill downregulating TNF-α/PI3K/p-Akt in gastritis and the Buyang huanwu decoction modulating the AKT1/MAPK1/PIK3CA axis against atherosclerosis." (PMID 40732361, 2025). "Our results indicated that compounds in Tualang honey such as luteolin, fisetin, hesperitin, catechin, and kaempferol may have a crucial impact on atherosclerosis through their effects on key biological targets, including PIK3CA, SRC, P1K3R1, EGFR, PTPN11, and AKT1." (PMID 37174317, 2023). "Therefore, CSJD may regulate targets such as PIK3CA, AKT1, TNF, IL-6, and others through the lipid and atherosclerosis pathway, block the key pathways and molecules of lipid metabolism, and thus achieve the effect of inhibiting dengue virus replication and improving clinical symptoms of patients." (PMID 38206728, 2023).
bladder urothelial carcinoma (5 papers, 2015 to 2023). "One additional TCGA cohort, bladder urothelial carcinoma, showed a significant association between FOXP1-SHQ1 deletion and PIK3CA mutation or amplification." (PMID 29057879, 2017). "Mutations in FGFR3 and PIK3CA, singly or combined with RAS and AKT1, are associated with AKT but not with MAPK pathway activation in urothelial bladder cancer." (PMID 34229750, 2021).
carcinoma in situ (5 papers, 2021 to 2024). "Further, three PIK3CA mutations were detected, namely a hotspot missense mutation (c.1624G > A, p.E542K) in an in situ carcinoma and two deletions ((twice c.3114delT:p.Y1038fs), one in a low-grade and one in a high-grade dysplasia sample)." (PMID 35173208, 2022).
clear cell renal cell carcinoma (5 papers, 2020 to 2024). "PIK3CA was found to have genetic alterations, and amplification or mutations were found in 5% of clear cell renal cell carcinomas." (PMID 36789694, 2022). "NGS analyses revealed KRAS gene mutation (c.35G > T/p.G12V in exon 2) in the papillary renal neoplasm with reverse polarity, with PIK3CA gene mutation restricted to the clear cell renal cell carcinoma (c.1624G > A/p.E542K in exon 10)." (PMID 33023600, 2020). "Chen and other experts declared that miR-490-5p is lowly expressed in the tissue and cells of clear cell renal cell carcinoma (ccRCC), and it constrains the growth of ccRCC via PIK3CA." (PMID 34594374, 2021). "Furthermore, PIK3CA mutations and increased mTOR signalling have been linked to poor response to ICB in other cancer types, including breast, colorectal and clear cell renal cancer." (PMID 38711203, 2024).
cortical dysplasia (5 papers, 2015 to 2021). "Mutations in the genes PIK3CA and PI4KA that encode phosphoinositide kinases are associated with polymicrogyria and cortical dysplasia, disorders that result in altered cerebral cortex morphology and cellular composition." (PMID 31507376, 2019). "A comprehensive study on 33 children with pediatric epilepsy identified germline mutations (PTEN) or mosaic activating mutations (PIK3CA and AKT3) in PI3K pathway genes which dramatically manifests as different forms of brain malformations like megalencephaly and cortical dysplasia." (PMID 31507376, 2019).
Hepatic fibrosis (5 papers, 2012 to 2023). The presence of excessive fibrous connective tissue in the liver. "Still, little is known about the precise role of PIK3CA in fibrosclerotic disorders, however, it has been proved that hepatic Akt expression correlated with advanced liver fibrosis in chronic hepatitis C patient." (PMID 22397327, 2012). "Additionally, there are 51 targets containing in both potential targets of DGLHD and liver fibrosis-associated targets, such as PTGS2, NF-κBp65, PPAR-γ, and PIK3CA, indicating the possible effects of DGLHD protecting against hepatic fibrosis." (PMID 29556199, 2018). "Based on these predictions, we selected PIK3CA, AKT1, HIF1A, VEGFA, and other related targets as the candidate targets of saffron for anti-hepatic fibrosis and conducted further experimental validation." (PMID 37959658, 2023). "Afterward, we collected 286 targets corresponding to active ingredients in DGLHD, including TNF-α, NF-κB, AP-1, PPAR-γ, PIK3CA, and MMPs, which were involved in inflammation, cell proliferation, or ECM deposition during the development of liver fibrosis." (PMID 29556199, 2018). "Activation of PI3K/Akt pathway is highly correlated with the development of liver fibrosis, this might explain why the upregulation of pik3ca was not in most of the fish with steatosis." (PMID 31795276, 2019).
hyperplasia (5 papers, 2009 to 2023). An abnormal increase in the number of cells in an organ or a tissue with consequent enlargement. "Data from the COSMIC database supports this idea, with PIK3CA mutation detected in 49% of hyperplasia, 29% of DCIS, and 24% in IDCs, suggesting the level of PIK3CA mutation decreases as disease progression ensues." (PMID 30813596, 2019).
kidney cancer (5 papers, 2017 to 2024). Primary or metastatic malignant neoplasm involving the kidney. "In summary, IQ can trigger the gene targets of PTGS2, IGF1R, and PIK3CA, which in turn regulate kidney cancer and inflammation." (PMID 38666938, 2024). "In our previous study, we also found that PTGS2, PIK3CA, IGF1R, and IL6 commonly caused kidney cancer and inflammation, and by suppressing these genes, we can reduce the severity of kidney cancer and inflammation." (PMID 38666938, 2024). "Our previous in silico protein–protein interaction (PPI) and molecular docking studies revealed that the isoquercitrin compound could trigger potential cancer-causing gene targets, such as IGF1R, PIK3CA, IL6, and PTGS2, which can regulate kidney cancer and inflammation." (PMID 38666938, 2024). "Our previous study predicted using protein-protein interaction (PPI) and molecular docking analysis that the isoquercitrin compound can control kidney cancer and inflammation by triggering potential gene targets of IGF1R, PIK3CA, IL6, and PTGS2." (PMID 38666938, 2024). "So, all results validated the finding that isoquercitrin treatment can suppress PTGS2, PIK3CA, and IGF1R expression and thus control kidney cancer and inflammation." (PMID 38666938, 2024). "Thus, we can conclude that isoquercitrin inhibits the expression of PTGS2, PIK3CA, and IGF1R gene targets, which in turn controls kidney cancer and inflammation." (PMID 38666938, 2024). "Furthermore, we performed in vitro validation of IQ efficacy using RT-PCR and qRT-PCR assays and confirmed that IQ can trigger PTGS2, PIK3CA, and IGF1R gene targets to control kidney cancer and inflammation." (PMID 38666938, 2024). "PIK3CA, IL1R1, HSP90AA1, and ATG5 were significantly lower expressed in tumor tissues (p < 0.05), which were further confirmed by the protein expression profile in kidney cancer downloaded from HPA database." (PMID 36932108, 2023).